CD163 (CD163 molecule)
Diseases named in the same sentence as CD163 in open-access papers (continued):
Sharing a sentence is not in itself a finding about the gene and the disease.
infection (continued). "Since most of them express CD163 and do not induce strong inflammation at infection sites, they are very likely anti-inflammatory M2 macrophages." (PMID 33315931, 2020). "In contrast, the present study was not able to show any increased level of CD163 in the plasma during infection with Bb in mice." (PMID 33036200, 2020). "Earlier in vitro studies supported CD163 as being a significant receptor for ASFV, demonstrating that monoclonal antibodies could block infection." (PMID 32478103, 2020). "The immune cells were stained with (C–D) anti-CD1a and anti-HIV-1 mAbs for DCs, (E–F) anti-CD163 and anti-HIV-1 mAbs for macrophages (G–H), and anti-CD3, anti-CD4, and anti-HIV-1 mAbs for CD4+ T cells and the level of infection was assessed by flow cytometry (N = 11–15)." (PMID 32876566, 2020). "Although CD163 was first suggested to be required for infection by ASFV, subsequent studies showed that monocytes that didn’t express CD163 could also be infected." (PMID 32515659, 2020). "Thus, “edited” pigs are fully resistant to infection by PRRSV and confirm CD163 as major PRRSV receptor." (PMID 30862035, 2019). "Considering that no significant alterations were observed in the expression of either surface-expressed or soluble CD163 during nonlethal infection, the results suggest that alterations in this molecule correlate with disease severity." (PMID 31570561, 2019). "Compared to the preinfection time point, the percentage of CD163+ anti-inflammatory macrophages was significantly reduced at 180 days post-infection in VEH/SIV but not in THC/SIV rhesus macaques." (PMID 31114576, 2019). "The expression of PRRSV ORF7 in CD163 SRCR5-edited PAMs was significantly lower than that of WT controls at all time points post infection, and PRRSV ORF7 was not expressed in CD163 SRCR5-edited PAMs at 24, 36, 48, and 60 hpi." (PMID 31440241, 2019). "The observed changes in MHC-II and CD163 expression were substantially more pronounced during lethal infection and primarily affected the nonclassical monocyte subset." (PMID 31570561, 2019). "Moreover, at 180 days post infection, THC/SIV rhesus macaques had a significantly higher percentage of CD163+ anti-inflammatory macrophages in the intestine compared to the VEH/SIV group." (PMID 31114576, 2019). "The results showed that the expression levels of M2 MΦ markers CD163 and CD206 increased significantly after infection in Raw246.7 cells, while BCA could reverse this trend partially." (PMID 30271755, 2018). "After infection with PRRSV-HuN4, we found that the PAM-Tang-low line, which contained 55.18% CD163-positive cells, showed limited PRRSV replication; however, PRRSV replicated efficiently in both the PAM-Tang-middle (68.4% CD163-positive cells) and PAM-Tang-high lines (82.88% CD163-positive cells)." (PMID 29552301, 2018). "CD163 is a cellular receptor that mediates productive infection of PRRSV in various nonpermissive cell lines." (PMID 29682543, 2018). "For the first time, we showed that cells with low CD163 abundance (approximately 20%) do not initiate PRRSV infection, while cells with moderate CD163 abundance display limited infection." (PMID 29552301, 2018). "Our data show that infection of MDMs, MDDCs, dMonWC1+, or dMonWC1neg with Map did not significantly alter surface expression of CD163, CD1b, CD205, CD14, CD172a, CD11b, or CD11c at 48 h post infection." (PMID 28588573, 2017). "Transfection of non-permissive cell lines with CD163 cDNA from a variety of species, including simian, human, canine, and mouse can make cells permissive for infection." (PMID 29042674, 2017). "Confocal microscopy revealed the absence of replication structures in the SRCR5 CD163 deletion macrophages, indicating an inhibition of infection prior to gene expression, i.e. at entry/fusion or unpacking stages." (PMID 28231264, 2017).
infection (continued). "The genes significantly impacted by infection only in CS included mast cell proteinase-3, γ-glutamyltransferase 5 (GGT5), CD163 as well as those involved in smooth muscle contraction, such as tropomyosin (TPM2), myosin, light chain 9, regulatory (MYL9), and calponin 1, basic, smooth muscle (CNN1)." (PMID 27197554, 2016). "Also a significant change in the expression (MFI) of the phenotypic markers CD14 (up), CD163 (down) and TLR4+ (down) was measured after infection in both groups." (PMID 27606818, 2016). "According to model A, PAMs can have one of three states prior to infection (or during mock infection): a priori CD163 negative, CD163 positive and CD163 negative after shedding of the receptor or the mAB binding domain." (PMID 27770812, 2016). "Interestingly, CD163 was significantly upregulated in the SS2 (3.6-fold) and H1N1-SS2 (4.98-fold) infection groups, however, it was downregulated in H1N1 infection group." (PMID 25906258, 2015). "A careful dissection of the transcription profile by day 1 pi in tissues from E75CV1-infected pigs, allowed the confirmation of the significant up-regulation of CD163, IL-1β, IFN-γ, IL-5, IL-6, IL-10, IL-12p40, TNF-α and TGF-βR1 and the down-regulation of DEFB2, immediately after E75CV1 infection." (PMID 26589145, 2015). "The role of CD163 as receptor for ASFV entry has been proposed but not universally supported since reports demonstrated efficient infection of macrophages that do not express CD163." (PMID 26589145, 2015). "No significant change in CD163 expression was observed during the course of infection indicating that the CD163− infected cells did not derive from down-regulation of CD163 after infection." (PMID 24398227, 2014). "The numbers of CD14hi/CD163- monocytes in BM, PB and UA of the lungs and spleen decreased after infection and they were not elevated in either organ except a small population in TBLN." (PMID 24134635, 2013). "As a damaged BBB is a potential route of viral entry early in infection, it is unclear why microglial activation via CD163 is not present prior to the development of SIVE." (PMID 22403025, 2012). "CD163 was shown to be a cellular receptor capable of mediating infection of otherwise PRRSV non-permissive cell lines." (PMID 21447173, 2011). "Non-permissive cells transiently transfected with CD163 allow a low level of infection depending on the cell type used." (PMID 20587060, 2010). "If the CHOSn-CD163 and PK15Sn-CD163 cells were treated with neuraminidase, infection of the PK15Sn-CD163 cells, but not the CHOSn-CD163 cells, with macrophage grown virus was increased." (PMID 20587060, 2010). "The aim of this study was to evaluate the utility of five markers of infection: C-reactive protein (CRP), procalcitonin (PCT), soluble triggering receptor expressed on myeloid cells-1 (sTREM-1), CD163 and high mobility group box-1 (HMGB1), as markers of SBI in severely ill Malawian children." (PMID 19675669, 2009). "The CD163 gene-edited pigs did not exhibit any clinical signs, such as fever or respiratory issues, and showed no lung pathology, viremia, or antibody response after infection." (PMID 40065264, 2025). "Cd163 was not upregulated by 4T1 but was reduced by infection." (PMID 40547518, 2025). "TNF, together with other receptor genes such as a scavenger receptor CD163 and Fc receptors, demonstrated that a TNF-mediated inflammatory response was triggered in iMACs, and the stimulated macrophages would engulf the HCV-infected Huh7 cells to relieve the infection." (PMID 38675895, 2024). "In the same report, it was suggested that the negative impact on infection could be due to modifications of the glycan structure of cell surface viral receptor, CD163." (PMID 38776134, 2024). "CD163 also appears to play a role in ASFV infection, although in this case it is not essential, as gene-edited pigs lacking CD163 were fully susceptible to infection by ASFV." (PMID 37626913, 2023).
infection (continued). "However, the infections of porcine macrophage cell lines expressing CD163 with different lineages of PRRSV have not been systematically investigated." (PMID 36146862, 2022). "Interestingly, localization of the virions in the early endosome was visualized at the beginning stage of infection in both wild-type and modified MARC-145 cells, but in the CD163 modified MARC-145 cells, localization of virions was only observed in the late endosome." (PMID 33916997, 2021). "Both young and old RMs showed increased infiltration of inflammatory immune cells (CD8+, CD163+, and CD11b+ cells) after infection, whereas inflammatory factor-secreting cells (IFN-α+, IL-6+, and IL-1β+ cells) were only significantly induced in old RMs following infection." (PMID 34471088, 2021). "In the cells collected after 48 h digestion, we observed a slightly but not statistically significant higher infection in the Lena-inoculated cells (4.2 ± 2.0%) than with LV-inoculated cells (1.5 ± 0.7%) (p = 0.073) and more than 90.4% of the infected cells were CD163+." (PMID 32093748, 2020). "Moreover, CD172a+/CD163−/MHC-II+ and CD172a−/CD163−/MHC-II+ cells exhibit strong migration and antigen-presenting capabilities, which can be credited to the increased influx of these cells into the lungs during the course of infection." (PMID 32404209, 2020). "However, recent work using knockout pigs lacking CD163 challenged with ASFV Georgia2007/1 were not protected from infection, demonstrating that CD163 is not crucial for viral entry, at least for this strain." (PMID 31547130, 2019). "The reason may be that, although virus uncoating and genome release are suppressed in CD163 SRCR5-partially deleted PAMs after PRRSV infection, the virion can adsorb and enter the cells during the early phase of infection, which might induce cytokine expression in SRCR5-edited cells." (PMID 31440241, 2019). "However, CD163 SRCR5-edited piglets showed no signs or symptoms of infection and survived the PRRSV challenge." (PMID 31440241, 2019). "The temperatures of CD163 SRCR5-edited piglets remained in the normal range and varied between 38.5 and 39.5°C, while the temperatures of WT piglets were 0.5-1 degree higher and they developed a clinical fever, persisting over 40°C for ~28 days post JXA1 infection." (PMID 31440241, 2019). "Interestingly, lethal infection also induced downregulation of CD163 on the surface of nonclassical monocytes." (PMID 31570561, 2019). "Therefore, we hypothesized that the addition of recombinant SRCR1-4 to PAMs would interfere with PRRSV internalization and sequential infection via competitive inhibition for MYH9 binding and thus would interrupt the endogenous CD163 and MYH9 interaction." (PMID 31447818, 2019). "Many studies have demonstrated that CD163 is an indispensable receptor for PRRSV infection, since the introduction of CD163 into non-permissive cell lines can confer susceptibility to infection and absolute resistance to PRRSV infection is observed in CD163 knock-out pigs." (PMID 31447818, 2019). "When assessing the ex vivo frequencies of CD163+ and MerTK+ double positive CD16+ monocytes we found that already at baseline rhesus macaques had significantly higher frequencies of MerTK+CD163+CD16+ monocytes, which were however markedly decreased from 3 weeks post-infection onward." (PMID 31736945, 2019). "Non-permissive cells transiently transfected with CD163 may allow a low level of infection depending on the cell type used for virus replication." (PMID 30021620, 2018). "For example, CD163+ macrophages, a noninflammatory subset, accumulate in the gut while inflammatory Mac387+ macrophages infiltrate the brain suggesting disparate roles for macrophages during infection." (PMID 29466439, 2018). "However, more recent studies have demonstrated that CD163 is not necessary for infection with the Georgia 2007/1 virus isolates." (PMID 28489063, 2017).
infection (continued). "Indeed, our process-based models informed by the experimental data do not support the view that CD163 is essential for productive infection of PAMs with PRRSV." (PMID 27770812, 2016). "At 7 days post-infection, M. mass-infected cells showed lower expression of CD68 (pan-macrophage marker present on lysosomal-associated membrane proteins), CD206 (mannose receptor) and CD163 (scavenger receptor) than non-infected cells." (PMID 27489303, 2016). "Consequently, we hypothesized that in addition to CD169 and CD163+ cells, PRRSV in utero infection is influenced by other factors involving epithelial cells of MFI and areolae." (PMID 27494990, 2016). "In contrast to model A, model B assumes that CD163 is not essential for infection with PRRSV." (PMID 27770812, 2016). "Moreover, an increasing proportion of PAMs apparently lacking CD163 were found susceptible to PRRSV at the later incubation stages, thus conflicting with current understanding that CD163 is essential for productive infection of PAMs with PRRSV." (PMID 27770812, 2016). "However, CD169 transfection enhances the infection efficiency of non-permissive cell lines expressing CD163." (PMID 27182980, 2016). "With the progression of the infection a more equilibrated immunological balance is observed, with 6 genes showing significant transcription up-regulation: IFN-γ, IL-5, TNF-α, TGF-βR1, IL-21 and IL-23 and 4 extra genes showing significant down-regulation: DEFB1, CD163, IL-13 and IL-18." (PMID 26589145, 2015). "However, in this study the expression of porcine CD163 on cell lines did not increase the infection rate of these cells indicating other factors are likely to be important in determining susceptibility to infection." (PMID 24398227, 2014). "Non-permissive cells transiently transfected with CD163 may allow a low level of infection depending on the cell type used." (PMID 20587060, 2010). "However, CD163 R561 was not essential for the virus’s infection." (PMID 40065264, 2025). "Interestingly, the SARS‐CoV‐2 peptides which exhibited sequence similarity with CCL3 and CCL3L1 (and CD163) were not homologous with HCoVs —which may increase the likelihood of being involved in immunopathology after infection." (PMID 35143694, 2022). "Interestingly, although CD163 SRCR5-edited PAMs were resistant to PRRSV infection and the expression of PRRSV ORF7 was undetectable at later infection time points, viral ORF7 mRNA was detectable at a very low level in SRCR5-edited cells at an early stage of infection." (PMID 31440241, 2019). "Recent results from CD163 knockout pigs indicate the complete absence of PRRSv-1 infection in PAMs and a substantial reduction in PRRSv-2, suggesting the pivotal role of CD163 in PRRSv-1 infection that may not be necessarily related with the length of the viremia." (PMID 29448955, 2018). "However, the role of CD163 in ASFV infection remains controversial since it was recently published that in non-permissive cells, CD163 expression is not enough to increase susceptibility to ASFV, and that CD163-knockdown pigs are not resistant to infection with ASFV Georgia 2007/1." (PMID 29117102, 2017). "Indeed, model B (CD163 not essential for infection) unanimously produced a close and a statistically superior fit over alternative model A (CD163 essential for infection) to the multi-variate data profiles for all eight pigs, and led to realistic and consistent estimates for the model parameters." (PMID 27770812, 2016). "Our study has therefore important implications for the development of vaccines or therapeutics that target CD163 expression in resident macrophages of pigs, as our findings would imply that simply reducing CD163 expression may not necessarily protect cells from infection with PRRSV." (PMID 27770812, 2016). "CD163+ and CD86+ TAMs were significantly more abundant in H.pylori-positive patients compared with those without infection (P < 0.001)." (PMID 41395618, 2025).
infection (continued). "Consistently, both PRRSV2 achieved similar infection levels in CD163-3D4/21 and MARC-145 cells, but no detectable infection levels in non-permissive 3D4/21 cells." (PMID 36146862, 2022). "Second, in infected CD163-3D4/21 cells, but not in MARC-145 cells, the CPE and viral N fluorescent signals were observed with both SD17-38 and Anheal-1 infections." (PMID 36146862, 2022). "Although gene-edited CD163 knockout (PRRV resistant) pigs and pAPN knockout (TGEV resistant) pigs have been previously generated, respectively, pigs that are resistant to the infection of both viruses are lacking." (PMID 32876563, 2020). "To rule out the effect of CD163 expression level on the tolerance of the cell lines, we extracted RNA from the different cell lines without PRRSV-EGFP infection." (PMID 32038556, 2019). "For a productive infection, the PRRSV requires trafficking only through CD163-positive EE, and not the late endosomes and lysosomes." (PMID 32038556, 2019). "Frequencies of circulating CD163+CD16+ monocytes, regardless of MerTK expression, remained higher in rhesus macaques up until week 3 post-infection." (PMID 31736945, 2019). "Conventional DC1 and cDC2 were negative for the two known PRRSV receptors CD163 and CD169, at steady state and upon infection." (PMID 30333837, 2018). "At 24 h post-infection, luciferase activity was evaluated, and the data suggested that PRV infection was not influenced by CD163 abundance." (PMID 29552301, 2018). "However, the role of these cells could be more complex, and CD163 IHC supplemented with cell quantification may not be sufficient to analyze the subtle mechanisms of reproductive disorders caused by PRRSV and the differences between the pathogenesis of PRRSV-1 and PRRSV-2 infection." (PMID 36899686, 2023). "The low level of PRRSV RNA that was initially detectable in the DKO line at 12 hpi is likely attributable to the adsorbed PRRSV independent of the existence of CD163, as CD163 is thought to be primarily responsible for the uncoating and viral RNA release processes of PRRSV infection." (PMID 32876563, 2020). "Therefore, we generated pigs lacking SRCR5 by the deletion of exon 7 of CD163 using CRISPR/Cas9 editing and showed that macrophages from these pigs were resistant to both PRRSV-1 and PRRSV-2 infection in vitro." (PMID 29925651, 2018). "While CD68 expression did not change with infection or treatment, Mtb infection resulted in the elevated expression of HLA-DR and CD200R, while activation markers such as CCR7, CD80/CD86, and CD64 as well as scavenger receptors CD163 and CD206 were reduced on Mtb-infected cells." (PMID 40305296, 2025).
cardiovascular disease (22 papers, 2011 to 2025). "Elevated levels of soluble CD163 (sCD163) have also been shown to be associated with arterial inflammation and cardiovascular disease in HIV-infected patients, although in this case sCD163 levels appear responsive to HIV therapy." (PMID 25544986, 2014). "Two of the proteins in the NLRC5 network (CD163 and FCGR3B) were also linked to cardiovascular diseases." (PMID 31900413, 2020). "In cardiovascular diseases, a high CD163/TWEAK ratio was found." (PMID 35898446, 2022). "In addition, research has demonstrated that CD163 serves as a critical link between the immune system, inflammatory response, and cardiovascular disease by not only reflecting the activation of immune cells, particularly macrophages, but also modulating immune responses." (PMID 40630963, 2025). "In cardiovascular disease, CD163+ elevation elicits the differentiation of a distinct, alternative, non–foam-cell anti-inflammatory macrophage that, in turn, promotes angiogenesis, leakiness, inflammation, and plaque progression via the CD163/HIF1α/VEGF-A pathway." (PMID 34367949, 2021). "Although CD163 interacts with TWEAK to regulate tissue regeneration after ischemic injury in vivo, the relevance of TWEAK/CD163 interaction in the context of cardiovascular disease needs to be explored." (PMID 32053869, 2020).